APP (amyloid beta precursor protein)
Diseases named in the same sentence as APP in open-access papers (continued):
Sharing a sentence is not in itself a finding about the gene and the disease.
Alzheimer disease (continued). "While it is well established that stroke and cerebral hypoperfusion are risk factors for Alzheimer's disease (AD), the molecular link between ischemia/hypoxia and amyloid precursor protein (APP) processing has only been recently established." (PMID 19705038, 2009). "Animal models of Alzheimer's disease, such as the APP transgenic line Tg2567 carrying the Swedish mutation, also show enhanced levels for TNF-α, IL-1β, IL-1α, chemoattractant protein-1, COX-2 and complement component 1q." (PMID 18564425, 2008). "Both aging and mutations in genes that encode amyloid precursor protein (APP) and presenilin (PS) are considered to be major risk factors for Alzheimer's disease (AD)." (PMID 18716656, 2008). "Accumulating evidence suggests that increased expression of the amyloid precursor protein gene (APP) increases Alzheimer's disease (AD) risk." (PMID 18684319, 2008). "The amyloid-β peptide (Aβ), implicated in the pathogenesis of Alzheimer's disease (AD), is produced through sequential proteolysis of the Aβ precursor protein (APP) by β- and γ-secretases." (PMID 19090992, 2008). "This retromer complex appears to play a crucial role in the transportation of transmembrane proteins implicated in Alzheimer's disease, such as amyloid precursor protein (APP) and β-site APP cleaving enzyme (BACE1)." (PMID 17903297, 2007). "There are a number of inherited forms of Alzheimer disease which are caused by mutations either in the protein from which Aβ is derived, called beta-amyloid precursor protein (shortened to APP) or in other proteins that act to release the Aβ protein from APP." (PMID 17760499, 2007). "Alzheimer's disease (AD) is characterized by abnormalities in post-translational processing of two proteins, the amyloid precursor protein (APP) and the microtubule associated protein tau." (PMID 17183681, 2006). "A successful example in psychiatry was the discovery of a Mendelian cause of Alzheimer's disease, located on chromosome 21 (mutations at the APP locus), due to the observation that Down syndrome patients show similar Alzheimer neuropathological features." (PMID 11120554, 2000). "Importantly, Alzheimer's disease-associated APP mutations further potentiate Hv1 activity, providing a mechanistic link between genetic risk factors and microglial dysfunction, offering APP-Hv1 as a new therapeutic target for neuroinflammatory disease." (PMID 41780099, 2026). "Amyloid-β (Aβ) is widely regarded as a key initiator of theneurodegenerative cascade in Alzheimer's disease (AD).Studies of pathogenic mutations in the amyloid precursor protein (APP) genehave greatly advanced understanding of Aβ biochemistry, aggregation, anddeposition." (PMID 41915856, 2026). "Aggregated Aβ peptides, hydroxyl radicals created by H2O2, and mitochondrial dysfunction caused by APP in Alzheimer's disease may be mitigated by pharmaceutical methods including phytochemicals which maintain mitochondrial dynamics." (PMID 39800464, 2025). "Variants in APP are associated with a decline in muscle mass and strength, and its abnormal processing leads to the production of Amyloid Beta (Aβ), a pathological hallmark of Alzheimer’s disease (AD)." (PMID 40435122, 2025). "The amyloid hypothesis suggests that the buildup of amyloid plaques around and on neurons is the primary cause of Alzheimer’s disease and is based on the accumulation of the product of the amyloid precursor protein (APP) gene located on chromosome 21." (PMID 40869138, 2025). "Universal hypotonia contributes to motor delays, while patients also face an increased risk of seizures, early-onset Alzheimer’s disease due to Amyloid Precursor Protein (APP) gene triplication, refractive errors, and conductive hearing loss, necessitating comprehensive and lifelong specialty care." (PMID 41597015, 2025).
Alzheimer disease (continued). "Differences in DNA methylation have been reported both in blood and brain tissue of Alzheimer’s disease cases compared to healthy controls, especially in gene regions associated with AD pathology, including apolipoprotein E (ApoE) and the amyloid precursor protein (APP) but also in other genes." (PMID 39853302, 2025). "APP is a ubiquitous membrane protein that has been observed to be associated with Alzheimer’s disease and with cerebral amyloid angiopathy; the products of APP cleavage have a variety of physiological roles that are important in neuronal development and neuronal function." (PMID 40870024, 2025). "Moreover, this population is at high risk of developing Alzheimer’s disease (AD), possibly due to the overexpression of the APP gene, which maps on chromosome 21." (PMID 40358801, 2025). "SARS‐CoV‐2 may also impact the initiation or progression of Alzheimer's Disease (AD), a progressive dementia associated with the accumulation of amyloid precursor protein (APP) and hyperphosphorylated tau protein." (PMID 40536011, 2025). "In addition, the onset of Alzheimer’s disease is also associated with the glycosylation of various proteins, including APP and Tau proteins." (PMID 41409784, 2025). "One peak in the promoter region of a transcript variant of APP gene exhibited further CN-independent increases, potentially boosting the expression of a specific variant of the APP protein and contributing to an increased risk of Alzheimer’s disease in individuals with DS." (PMID 40155863, 2025). "APOE4 and APP are two of the main genetic risk factors for Alzheimer’s disease (AD)." (PMID 41211332, 2025). "However, the accumulation of amyloid-ß over an extended period and/or elevated levels of APP expression (and elevated levels of APP processing) are associated with Alzheimer’s disease." (PMID 40302938, 2025). "Numerous genes involved in the pathogenesis of Alzheimer disease have been described so far, including, but not limited to, mutations in amyloid precursor protein (APP), presenilin 1 and 2 (PSEN1 and PSEN2), and carrying the E4 allele of Apolipoprotein (ApoE) genes." (PMID 39199306, 2024). "APP is famously associated with Alzheimer’s disease, but its role in PD might relate to Aβ accumulation and its effects on neuronal health." (PMID 39264583, 2024). "Amyloid precursor protein (APP), especially Swedish mutant APP (APPswe), is recognized as a significant pathogenic protein in Alzheimer's disease, but limited research has been conducted on the correlation between APPswe and the osteogenic differentiation of mesenchymal stem cells (MSCs)." (PMID 40330152, 2024). "Various studies have shown that APP can propagate tau accumulation, implying that increased APP production in brains with Alzheimer’s disease may be associated with tau pathology." (PMID 39596378, 2024). "Furthermore, astrocytic Srf deletion in the APP/PS1 mouse model of Alzheimer’s disease causes a significant decrease in β-amyloid plaque burden." (PMID 38289036, 2024). "APP, a transmembrane protein, is unquestionably associated with Alzheimer’s disease but also serves crucial physiological functions for neuronal migration, neuronal morphology, synaptic plasticity, learning and memory, and more recently also for ASD-like abnormalities." (PMID 38745463, 2024). "The protein encoded by APP is essential to the pathophysiology of Alzheimer’s Disease." (PMID 38907247, 2024). "When combining the optimized thiophene‐vinyl‐benzothiazole based ligands with a conventional ligand, CN‐PiB, distinct staining patterns were observed for sporadic Alzheimer's disease versus dominantly inherited Alzheimer's disease caused by the Arctic APP E693G mutation." (PMID 39508558, 2024). "Additionally, partial duplication of the APP locus on chromosome 21 and rare cases of trisomy involving APP have been found to be causative factors in the development of early-onset Alzheimer’s disease neuropathology." (PMID 38474215, 2024).
Alzheimer disease (continued). "Importantly, research on proliferative DR in mice revealed associations between amyloid-beta precursor protein (APP) gene expression and Alzheimer’s disease (AD) risk genes identified through GWAS." (PMID 39723239, 2024). "Thus, genetic evidence showcases APP as a common denominator causatively linked to Alzheimer’s disease." (PMID 38992438, 2024). "Familial Alzheimer's disease is characterized by a strong genetic component and is typically associated with mutations in specific genes, including those coding for amyloid precursor protein (APP), presenilin 1 (PSEN1), and presenilin 2 (PSEN2)." (PMID 38169888, 2024). "APP gene dosage is strongly associated with Alzheimer’s disease pathogenesis." (PMID 38527856, 2024). "Additionally, Fe65 has been implicated in Alzheimer's disease through its links to APP processing and mediating transcriptional activities." (PMID 38799759, 2024). "Misprocessing of amyloid precursor protein (APP) is one of the major causes of Alzheimer’s disease." (PMID 39591990, 2024). "APP gene dosage is strongly associated with Alzheimer’s disease (AD) pathogenesis." (PMID 38527856, 2024). "The primary pathological hallmark of Alzheimer’s disease (AD) is the presence of extracellular senile plaques composed of aggregates of fibrillar amyloid β (Aβ) peptides, derived from the proteolytic processing of amyloid precursor protein (APP)." (PMID 39329779, 2024). "FERMT2 has been found to interact with integrins to regulate many physiopathological processes; most notably, FERMT2 has been identified as being associated with amyloid precursor protein (APP) metabolism, which is a significant risk factor for Alzheimer's disease (AD)." (PMID 38352691, 2024). "The AiCPP model was utilized to identify potential cell-penetrating peptides (CPPs) in the human amyloid precursor protein (APP), a 770-amino acid protein that is sometimes mutated, leading to the aggregation of amyloid beta and the development of Alzheimer’s disease." (PMID 36979457, 2023). "APP duplication is a rare genetic cause of Alzheimer disease and cerebral amyloid angiopathy (CAA)." (PMID 37170141, 2023). "Aβ peptide, the APP fragment associated with plaques in Alzheimer’s disease (AD), may lead to microcephaly via disruption of neurogenesis, elongation of the G1/S cell cycle, and arrested cell cycle promoting apoptosis." (PMID 37808474, 2023). "Dominantly inherited mutations in the amyloid precursor protein gene (APP) that cause disease are a mainstay of the amyloid cascade hypothesis of Alzheimer’s disease (AD)." (PMID 36611124, 2023). "For example, sortilin is genetically associated with Alzheimer’s disease (AD), regulates several aspects of amyloid precursor protein (APP) and amyloid-β (Aβ) trafficking and processing, and facilitates endocytic uptake of apolipoprotein E, the most important genetic risk factor for late-onset AD." (PMID 37949230, 2023). "Alzheimer’s disease is associated with various factors, including APP, PSEN1, PSEN2, and APOE." (PMID 37240173, 2023). "Familial Alzheimer’s disease (FAD) is known to be associated with mutations in the APP, PSEN1, and PSEN2 genes involved in Aβ production; however, these genetic defects occur in only about 10–20% of FAD cases, and more genes and new mechanism causing FAD remain largely obscure." (PMID 37365538, 2023). "Familial mutations in APP cause highly penetrant, autosomal dominant forms of Alzheimer’s disease." (PMID 37923712, 2023). "To test this hypothesis, we used the 5xFAD mouse model of Alzheimer’s disease that expresses human APP and presenilin 1, encoding five human pathogenic mutations that cause familial Alzheimer’s disease." (PMID 37171075, 2023). "Mutations in the APP gene are linked to rare familial forms of Alzheimer’s disease." (PMID 37623767, 2023).
Alzheimer disease (continued). "Fmr1KO mice overexpress amyloid precursor protein (APP) through an mGluR5-dependent pathway, and the J20 mouse model of Alzheimer’s disease that over-expresses APP with familial mutations exhibits a deficit in REM sleep, which is rescued with the mGluR5 inhibitor CTEP." (PMID 37833907, 2023). "Down syndrome (DS) is caused by triplication of chromosome 21, which harbors genes associated with Alzheimer’s disease (AD)-related proteins, including amyloid precursor protein (APP) and midbrain kinase/dual-specificity tyrosine phosphorylated and regulated kinase 1A (DYRK1A)." (PMID 37511361, 2023). "Mutations in the APP found in familial cases of Alzheimer’s disease may also cause chromosome mis-segregation leading to aneuploidy." (PMID 36266706, 2022). "The APP gene is one of approximately 250 protein-coding genes located on Chr21, and its duplication is associated with elevated Aβ production and increased incidence of Alzheimer’s disease (AD) neuropathology in most aged individuals with DS." (PMID 36343257, 2022). "In addition, Vac14 physically interacts with amyloid precursor protein (APP), the central player in Alzheimer's disease, and synphilin-1, an aggregation-prone protein implicated in Parkinson's disease." (PMID 36493904, 2022). "Overlapping of different degenerative diseases is a frequent phenomenon, for example, in patients with Alzheimer’s disease (AD), where around 50–60% of sporadic and genetic patients, carrying pathogenic mutations in APP, PSEN1, or PSEN2 genes, manifest widespread α-synuclein pathology." (PMID 35893043, 2022). "However, only 5–10% of patients with early-onset Alzheimer’s disease are carrying a pathogenic mutation in APP, PSEN1, PSEN2, or the common apolipoprotein E (APOE) ɛ4 allele." (PMID 36077172, 2022). "To investigate whether the effects of APP-CTFs accumulation on mitophagy in Alzheimer’s disease were related to PSEN mutation, we generated induced neural stem cells (iNSCs) from fAD patient-derived fibroblasts, as described in our previous study." (PMID 35013145, 2022). "APP mutations cause early onset familial forms of Alzheimer’s disease (FAD) in humans." (PMID 36438008, 2022). "The same study reports the involvement of other natural anti-sense transcripts in the regulation of Amyloid-beta precursor protein (APP), which is associated with Alzheimer’s disease, and α-synuclein which is associated with Parkinson’s disease and Lewy body dementia." (PMID 36467612, 2022). "BACE1 is also linked to pathophysiological processes, in particular to Alzheimer’s disease where it is a major drug target because it cleaves the amyloid precursor protein (APP) and catalyzes the first step in the generation of the amyloid β peptide, a key pathogenic agent in Alzheimer’s disease." (PMID 34958451, 2022). "APP encodes the β-amyloid precursor protein that has an important role in the development of neurodegenerative pathologies such as Alzheimer disease because of the accumulation of its derivative amyloid-beta (Aβ) peptide, which is induced by cleavage from secretases including the γ-secretase." (PMID 35077669, 2022). "APP genetic variants are often observed in Familial Alzheimer’s disease (FAD)." (PMID 36552984, 2022). "The finding that the knock-in of the Alzheimer’s disease-linked London mutation in APP in in vitro differentiated human neurons also resulted in a drop in TTL compared to isogenic controls strongly supports a causal relationship between TTL loss and familial Alzheimer’s disease." (PMID 35148384, 2022).
Alzheimer disease (continued). "In DS individuals, the increased risk of early‐onset Alzheimer's disease is related to the trisomic dosage of the genes for amyloid precursor protein (APP, OMIM #104760) and β secretase 2 (BACE2, OMIM #605668), essential proteins for amyloid‐beta (Aβ) peptide production." (PMID 35411714, 2022). "APP is a well-characterized causative protein of Alzheimer’s disease." (PMID 35524265, 2022). "Amyloid precursor protein (APP) has also been implicated in Alzheimer’s disease but nevertheless may be associated with MS." (PMID 35682558, 2022). "The amyloid hypothesis suggested that extracellular amyloid beta (Aβ) deposition in the brain is the pathological underlying cause of Alzheimer’s disease, due to the mutation in β-amyloid precursor protein (APP) gene." (PMID 36079752, 2022). "Accordingly, based on several GWAS studies, VPS10p-D receptors exhibit key functions in the causal pathways influencing Alzheimer’s disease risk such as APP catabolic processes, cholesterol and lipid metabolism, endocytosis, cellular sorting and trafficking, and immune responses." (PMID 36397124, 2022). "Alzheimer’s disease (AD), a common form of dementia, is caused in part by the aggregation and accumulation in the brain of amyloid β (Aβ), a product of the proteolytic cleavage of amyloid precursor protein (APP) in endosomes." (PMID 36142484, 2022). "SIGNIFICANCE STATEMENT Trisomy of chromosome 21 is a commonly occurring genetic risk factor for early-onset Alzheimer's disease (AD), which has been previously attributed to people with Down syndrome having three copies of the amyloid precursor protein (APP) gene, which is encoded on chromosome 21." (PMID 35835549, 2022). "The APP processing by γ-secretase through the amyloidogenic pathway results in the generation of Amyloid beta (Aβ), often linked with the pathological progression of the Alzheimer’s disease (AD)." (PMID 34645511, 2021). "The PS/γ-secretase complex was first discovered by its association with Alzheimer’s disease (AD); dominantly inherited mutations that resulted in early onset of AD were identified on the genes encoding PS and its substrate, the amyloid precursor protein (APP)." (PMID 34073182, 2021). "In addition, SORL1, a gene associated with amyloidogenic processing of amyloid-beta precursor protein (APP) and Alzheimer's disease risk, was upregulated in aged β-cells, along with its ligand highly expressed in all four kinds of aged islet cells." (PMID 34691567, 2021). "Additionally, known highly penetrant genetic variants from familial-based cohorts with early-onset Alzheimer’s disease (EOAD) implicate genes such as APP, PSEN1, and PSEN2." (PMID 33947463, 2021). "In addition, BRI2 interacts with and modulates proteolytic processing of amyloid-β precursor protein (APP), whose mutations cause familial forms of Alzheimer's disease (AD) (familial AD)." (PMID 34416235, 2021). "For example, changes the miRNA carried by EVs, such as a loss of miR‐101 which is associated with an increase in amyloid precursor protein (APP) could be used as an early detection method in Alzheimer's disease." (PMID 33857352, 2021). "Amyloid precursor protein (APP) is linked to Alzheimer’s disease." (PMID 33465062, 2021). "Proximity ligation assays were used to quantify CB2-NMDA heteromer expression in mouse primary cultures and in the brain of APPSw/Ind transgenic mice, an Alzheimer’s disease model expressing the Indiana and Swedish mutated version of the human amyloid precursor protein (APP)." (PMID 34749800, 2021). "The two top biological networks of these targets are centered on two proteins associated with neurodegeneration, the amyloid precursor protein APP that is associated with Alzheimer’ disease and Huntingtin (HTT), a genetic mutation associated with Huntington’s disease." (PMID 34571817, 2021).